SNHG7 (small nucleolar RNA host gene 7)
Synonyms: MGC16037; NCRNA00061
Gene: Long non-coding RNA gene on chromosome 9 (136,721,366 to 136,728,961, reverse strand). Ensembl gene ENSG00000233016.
Gene Ontology:
Biological process: RNA processing
Cellular component: nucleolus
Diseases named in the same sentence as SNHG7 in open-access papers:
SNHG7 is named in the same sentence as 68 diseases in open-access papers, as found by Europe PMC text mining. Sharing a sentence is not in itself a finding about the gene and the disease. The quoted sentences say what the papers report.
colorectal cancer (17 papers, 2019 to 2025). A primary or metastatic malignant neoplasm that affects the colon or rectum. "Highly expressed SNHG7 is associated with a poor prognosis in colorectal cancer." (PMID 35712981, 2022). "Our findings suggest the existence of an SNHG7/miR-133b/CDKN2A network that potentially acts to inhibit cuproptosis in colorectal cancer." (PMID 38888512, 2024). "It has been reported that small nucleolar RNA hostgene 7 (SNHG7) can sponge microRNAs to regulate colorectal cancer (CRC) progression." (PMID 36691432, 2023). "Previous studies showed that SNHG7 was upregulated in several cancers, such as glioblastoma, colorectal cancer, gastric cancer and esophageal cancer." (PMID 32066502, 2020). "In several cancers, including colorectal cancer, prostate cancer, esophageal cancer, lung cancer and gastric cancer, lncRNA SNHG7 has been known as a potent oncogene by targeting GALNT1, Cyclin D1, FAIM2, p15 and p16." (PMID 30853913, 2019). "Furthermore, related studies have identified ASMTL-AS1 and LINC02604 lncRNAs as novel biomarkers for CRC, while SNHG7 also influences the progression of colorectal cancer by regulating the PI3K/Akt pathway." (PMID 40723340, 2025). "Noteworthy, recent studies revealed that SNHG7 has a regulatory role in colorectal cancer." (PMID 35747807, 2022). "Previous study reported that miR-34a was a target miRNA of SNHG7 in colorectal cancer." (PMID 32066502, 2020). "A previous study showed that miR-34a-5p was a target of SNHG7 in colorectal cancer progression." (PMID 32066502, 2020). "Analysis of the TCGA data showed that the expression of three lncRNAs—SNHG7, ASMTL-AS1, and LINC02604—that had the highest interaction with other miRNAs and mRNAs identified based on the ceRNA network was increased in colorectal cancer." (PMID 39028420, 2024). "It has been reported that SNHG7 acts as a ceRNA by sponging miR-34a, which controls the expression of the GALNT7 target gene and promotes the progression of colorectal cancer (CRC) via the PI3K/Akt/mTOR pathway." (PMID 39028420, 2024). "For example, SNHG7 is an oncogenic biomarker in COAD, and it interacts with miR-193b and positively regulates GALNT1 levels through sponging miR-216b in colorectal cancer." (PMID 35747807, 2022). "Moreover, SNHG7 and FAIM2 are upregulated in colorectal cancer tissues compared with normal adjacent tissues." (PMID 35747807, 2022). "SNHG7, whose high expression was correlated with poor prognosis, acted as a target of miR-34a to increase GALNT7 level and regulate PI3K/Akt/mTOR pathway in colorectal cancer progression." (PMID 31164492, 2019). "In addition, it has been reported that SNHG7 may conduct as an oncogene in colorectal cancer (CRC) progression, and increased expression of SNHG7 is related to cell proliferation, inhibition of cell apoptosis, and enhancement of liver metastasis of CRC." (PMID 34714775, 2021).
breast carcinoma (16 papers, 2018 to 2025). "It has been found that dysregulation of SNHG7 associated with growth and progress of different kinds of cancer, such as breast cancer, pancreatic cancer, hepatocellular carcinoma and cervical cancer." (PMID 34714775, 2021). "In our study, we further found that the expression of SNHG7 was upregulated in chemoresistant breast cancer, which was also associated with an adverse response to NAC and poor RFS." (PMID 33330080, 2020). "For instance, SNHG7 was described as an EMT-promoter in breast cancer cells, where it sponged miR-34a, leading to the activation of the Notch-1 pathway." (PMID 38948025, 2024). "The knockdown of small nucleolar RNA host gene 7 (SNHG7) has been reported to increase the paclitaxel treatment efficiency in breast cancer cells by sponging miR-34a." (PMID 36613528, 2022). "For example, in two distinct experiments, enhanced sensitivity of breast cancer cells to Adriamycin and Trastuzumab is shown when SNHG7 is silenced or its target sponged miRNA (miR-34a or miR-186, respectively) is overexpressed." (PMID 35111760, 2021). "The expression of SNHG7 was upregulated in breast cancer and was positively correlated with tumor stage, lymph node metastasis and distant metastasis." (PMID 33330080, 2020). "SNHG7 regulates proliferation of breast cancer cell lines in a dose-dependent manner, and silencing SNHG7 expression causes cell cycle arrest in G0/G1." (PMID 32444795, 2020). "Knockdown of SNHG7 decreased cell viability, enhanced drug-induced apoptosis and facilitated drug sensitivity in breast cancer cells." (PMID 33330080, 2020). "An MTT assay revealed that knockdown of SNHG7 facilitated drug sensitivity of breast cancer cells, but nevertheless, the inductive effect of SNHG7 inhibition on drug sensitivity of breast cancer cells was patently abolished by miR-34a downregulation." (PMID 33330080, 2020). "Our results further verified that knockdown of SNHG7 facilitated drug sensitivity of breast cancer cells through miR-34a overexpression." (PMID 33330080, 2020). "High expression of SNHG7 accelerates breast cancer tumorigenesis and progression by sponging miR-34a to activate EMT and Notch-1 pathway." (PMID 33330080, 2020). "The present study aims to investigate the functions of SNHG7 in regulating chemoresistance in breast cancer and to preliminarily explore its potential molecular mechanism." (PMID 33330080, 2020). "The expression of SNHG7 in 5 breast cancer cell lines (MCF-7, T47D, SKBR3, MD-MB231, BT549) and normal human breast epithelial cell line (MCF-10A) determined by qRT-PCR." (PMID 33330080, 2020). "In terms of the mechanism, miR-34a was found to be a target of SNHG7 and its expression in breast cancer tissues and chemoresistant cell lines was negatively correlated with SNHG7 expression." (PMID 33330080, 2020). "Accordingly, we sought to confirm the clinical impact of extreme levels of SNHG7 in the tumors of breast cancer patients in the METABRIC45 dataset that includes rich and long-term clinical data from over 2000 patients." (PMID 32444795, 2020). "SNHG7 promotes the proliferation, migration, and invasion and inhibits apoptosis in many cancers, such as malignant pleural mesothelioma, breast cancer, chromophobe renal cell carcinoma, and lung cancer." (PMID 29970122, 2018). "Recent studies showed that SNHG7 was correlated with breast cancer, chromophobe renal cell carcinoma, and lung cancer." (PMID 29970122, 2018). "SNHG7 is overexpressed in breast cancer tissues and related to chemoresistance." (PMID 41181715, 2025). "Therefore, downregulating c-Myc and SNHG7 expression tends to be not only an efficient approach for regulating glycolysis but also a promising strategy to find new treatments for reprogramed breast cancer." (PMID 36230935, 2022).
breast carcinoma (continued). "SNHG7 has also been connected to breast cancer pathogenesis and metastasis through a number of studies showing that breast cancer cells and tissues express elevated SNHG7 levels that are correlated to tumor stage, distant metastasis, lymph node metastasis, and reduced overall survival." (PMID 36139687, 2022). "In breast cancer (BC), some researchers suggested that the increased expression of SNHG7 could promote tumorigenesis and progression by EMT initiation and the activation of the Notch-1 pathway through interacting with miR-34a." (PMID 34714775, 2021). "SNHG7 located at 9q34.3 is a potential molecular marker for malignant tumors, such as pancreatic cancer, osteosarcoma, esophageal cancer, bladder cancer, colorectal cancer, and breast cancer, cervical cancer, as well as gastric cancer." (PMID 34512753, 2021). "We propose that SNHG7 is a lncRNA oncogene that is controlled by growth factor signaling in a feedback mechanism to prevent hyperproliferation, and that this regulation can be lost in the development or progression of breast cancer." (PMID 32444795, 2020). "SNHG7 is a newly recognized lncRNA that is significantly upregulated in breast cancer." (PMID 33330080, 2020). "This further argues that SNHG7 has an important biological and clinical role in breast cancer." (PMID 32444795, 2020). "Collectively, SNHG7 knockdown facilitated drug sensitivity in breast cancer cells." (PMID 33330080, 2020). "Finally, we show in clinical data that SNHG7 is overexpressed in tumors of a subset of breast cancer patients and that these patients have lower disease-free survival than patients without elevated SNHG7 expression." (PMID 32444795, 2020). "The expressions of SNHG7 were detected in 43 cases of breast cancer tissue samples by RT-qPCR." (PMID 33330080, 2020). "In summary, the results of the present study indicated that high expression of SNHG7 may be a predictor of chemoresistance in breast cancer." (PMID 33330080, 2020). "Interestingly, SNHG7 was upregulated not only in CRC but also in breast cancer, lung cancer, and malignant pleural mesothelioma." (PMID 29915311, 2018). "Furthermore, the knockdown of lncRNA SNHG7 reduces drug resistance and inhibits stemness in breast cancer cells via miR‐34a, which indicates that lncRNA SNHG7 may be a potential therapeutic target to overcome chemoresistance in breast cancer patients." (PMID 33330080, 2020). "Therefore, the role of SNHG7 in the stemness of breast cancer cells was investigated in this study." (PMID 33330080, 2020). "Because SNHG7 is highly expressed, robustly regulated by IGF1 signaling, and is altered in a subset of breast cancer patients that correlate with survival, it was investigated further." (PMID 32444795, 2020). "Our results that IGF-regulated lncRNAs, including SNHG7 and SNHG15, are important for biology, enriched in breast cancer subtypes, and correlate with survival are consistent with recent studies." (PMID 32444795, 2020). "However, further understanding of the IGF1/SNHG7 system, the mechanisms of SNHG7 functions, and the characterization of other IGF1-regulated lncRNAs clearly will impact our understanding of both basic and breast cancer biology." (PMID 32444795, 2020). "Accordingly, SNHG7 is overexpressed or amplified in ~5% of TCGA breast cancer patients, and these patients have worse disease-free survival than those without SNHG7 alterations." (PMID 32444795, 2020).
gastric cancer (13 papers, 2019 to 2025). A primary or metastatic malignant neoplasm involving the stomach. "Some lncRNAs affect the glycolysis process by regulating the expression of key enzymes of glycolysis and inducing drug resistance in gastric cancer cell lines; these include, for instance, SNHG7, HAGLR, and SNHG1." (PMID 38927012, 2024). "In GC induced by exposure to environmental chemical carcinogens, METTL3 promotes the expression of SNHG7 by increasing the m6A methylation level of the lncRNA SNHG7 and promotes the malignant progression of gastric cancer." (PMID 39678510, 2024). "A recent study found that SNHG7 directly binds to miR-34a and enhances migration and invasion of gastric cancer cells by inhibiting the miR-34a-Snail-EMT axis." (PMID 39195675, 2024). "Rescue experiments confirmed that SNHG7 regulated the gastric cancer cells malignant behavior via the regulation of miR-485-5p." (PMID 34512753, 2021). "Here, we conducted a preliminary study on SNHG7 expression in gastric cancer, as well as its functions and regulatory mechanisms." (PMID 34512753, 2021). "The results revealed that SNHG7 expression in gastric cancer tissues was significantly higher than that of adjacent tissues." (PMID 34512753, 2021). "It was also found that the expression of SNHG7 in HS746 T cells was higher than that in other gastric cancer cells." (PMID 34512753, 2021). "Currently, this study intends to explore the expression and role of SNHG7 and the possible molecule mechanisms in gastric cancer." (PMID 34512753, 2021). "This study aimed to provide new biomarkers for the early diagnosis and treatment of gastric cancer by exploring SNHG7 expression and its effect and mechanism in gastric cancer." (PMID 34512753, 2021). "Findings suggested that SNHG7 expression was obviously enhanced in all gastric cancer cells versus GES1." (PMID 34512753, 2021). "In order to explore the molecular mechanism of SNHG7 regulating the biological behavior of gastric cancer cells, we predicted miRNAs targeted by SNHG7." (PMID 34512753, 2021). "This study investigated the effect of SNHG7 on gastric cancer progression and its potential molecular mechanism." (PMID 34512753, 2021). "METTL3 also increased the stability of multiple lncRNAs like MALAT1, THAP domain containing seven antisense RNA 1 (THAP7-AS1), small nucleolar RNA host gene 7 (SNHG7) and promotes various cancers progression including glioma, gastric cancer and prostate cancer." (PMID 40510136, 2025). "SNHG7 desensitizes gastric cancer cells to cisplatin via the miR-34a/LDHA-glycolysis axis." (PMID 38927012, 2024). "Taken together, interference with the expression of SNHG7 might provide a critical theoretical basis for inverting the malignant transformation of gastric cancer in clinical practice." (PMID 37999596, 2023). "Knockdown of SNHG7 could notably inhibit the gastric cancer cells proliferation, migration, and invasion." (PMID 34512753, 2021). "SNHG7 knockdown could hamper gastric cancer progression via inhibiting miR-485-5p expression, providing a novel understanding for gastric cancer development." (PMID 34512753, 2021). "At the same time, knockdown of SNHG7 in gastric cancer cells was found to increase miR-485-5p expression, indicating that SNHG7 could negatively regulate miR-485-5p." (PMID 34512753, 2021). "The results found that SNHG7 expression was increased in gastric cancer." (PMID 34512753, 2021). "SNHG7 expression was increased in human gastric cancer tissues and cells." (PMID 34512753, 2021). "Interestingly, miR-485-5p expression negatively correlated with SNHG7 expression in gastric cancer tissues." (PMID 34512753, 2021). "In summary, expression of SNHG7 was significantly reduced, and SNHG7 inhibition could repress the biological behavior of gastric cancer cells." (PMID 34512753, 2021). "Interestingly, miR-485-5p expression was decreased and was inversely related to SNHG7 expression in gastric cancer tissues." (PMID 34512753, 2021).
gastric cancer (continued). "First, we measured the expression of SNHG7 in gastric cancer." (PMID 34512753, 2021). "Similarly, SNHG7 also contributed to the progression and development of gastric cancer." (PMID 34512753, 2021). "However, there are few studies on the molecular mechanism of SNHG7 in gastric cancer." (PMID 34512753, 2021). "Besides, whether SNHG7 affects gastric cancer cell biological behavior through miR-485-5p was also explored." (PMID 34512753, 2021). "Results suggested that SNHG7 inhibition may hamper the progression of gastric cancer." (PMID 34512753, 2021). "Small nucleolar RNA host gene 7 (SNHG7), an oncogenic long non-coding RNA, promotes cell migration via the miR-34a-Snail-EMT axis in gastric cancer." (PMID 34830941, 2021). "Another example in gastric cancer is lncRNA SNHG7 (small nucleolar RNA host gene 7), which directly binds to miR-34a and suppresses the miR-34a–SNAIL–EMT axis, which regulates gastric cancer cell migration and invasion." (PMID 31947678, 2020). "To investigate whether there were differences in the expression of SNHG7 between gastric cancer cells and human normal gastric epithelial cells, we tested SNHG7 expression in, HS746 T, HGC-27, SNU-1, and AGS, four gastric cancer cells." (PMID 34512753, 2021).
bladder cancer (10 papers, 2020 to 2024). "SNHG7 acts as a sponge for miR-2682-5p to enhance the expression of ELK1, and the high expression of SNHG7 promotes the growth, migration, and invasion of bladder cancer cells." (PMID 39195675, 2024). "Furthermore, lncRNA SNHG7 sponging miR216b promotes liver metastasis of CRC by up-regulating GALNT1, while down-regulation of SNHG7 can inhibit the phenotype of malignant bladder cancer." (PMID 36115953, 2022). "SNHG7 activity in bladder cancer also extends to the activation of WNT/β-catenin pathway." (PMID 32318335, 2020).
lung carcinoma (10 papers, 2017 to 2025). "In lung cancer, exosomal SNHG7 enhances docetaxel resistance in LUAD cells by inducing autophagy and promoting the polarization of M2 macrophages, which may provide clues for ways to reduce the likelihood of chemotherapy failure in lung cancer." (PMID 36685535, 2022). "SNHG7 overexpression has been found in lung cancer, and SNHG7 could promote lung cancer cells proliferation, invasion, and inhibit apoptosis by enhancing the FAIM2 expression." (PMID 29047230, 2017). "In addition, a recent study showed that SNHG7 overexpression promotes cell migration and invasion in lung cancer by enhancing the FAIM2 expression." (PMID 29047230, 2017). "Overexpression of small nucleolar RNA host gene 7 (SNHG7) has been reported in most human tumors, including lung cancer, and it acts as an oncogenic lncRNA in GC and may be a promising therapeutic candidate for GC patients." (PMID 36310592, 2022).